PCNA (proliferating cell nuclear antigen)
Diseases named in the same sentence as PCNA in open-access papers (continued):
Sharing a sentence is not in itself a finding about the gene and the disease.
tumor (continued). "It is noteworthy that AKAP4 knockdown markedly inhibited the tumor growth with reduced AKAP4 and PCNA expression." (PMID 26590805, 2015). "Quantification of double positive cells for PCNA and GFP showed higher number of tumor proliferating cells in mice injected with AC cells than in mice injected with TSC cells (p < 0.001)." (PMID 26318423, 2015). "The IHC analysis results revealed that the number of lipid vacuoles and the expression of PCNA, Ki67, CDK2, and CDK4 were significantly greater in tumor tissues obtained from the mice fed on the HFD as compared to those of CD-fed mice." (PMID 25912035, 2015). "Considering this, we analyzed the expression of p-AKT, AKT, and its downstream molecule proliferating cell nuclear antigen (PCNA), a key player in cancer cell proliferation, in the tumor tissues." (PMID 26345456, 2015). "A proliferating cell nuclear antigen (PCNA) immunoreactivity analysis and a TUNEL assay found that miR-150 suppressed tumour cell proliferation and promoted cell apoptosis in vivo." (PMID 25230975, 2014). "Following the administration of α-solanine (6 μg/g for 2 weeks) in xenograft model, tumor volume and weight were decreased by 61% and 43% (p<0.05) respectively, showing decreased MMP-2/9, PCNA and VEGF expression." (PMID 24505326, 2014). "We assessed tumor cell proliferation in relation to HPGDS transgenes, by use of immunohistochemistry with anti-PCNA antibodies." (PMID 24729479, 2014). "A PCNA immunoreactivity analysis and a TUNEL assay found that c-Myb-siRNA suppressed tumour cell proliferation and promoted cell apoptosis in vivo." (PMID 25230975, 2014). "PRDM1 can also promote the apoptosis of tumour cells by specifically suppressing MKI67 and proliferating cell nuclear antigen." (PMID 24438193, 2014). "Increased PCNA and β-catenin expression suggested that DSS/AOM-induced neoplasm resembled human caCRC." (PMID 24766737, 2014). "Our results are in agreement to the previous report wherein the decrease in the expression of PCNA and CD31 has been correlated with reduction of tumor size and overall disease free survival." (PMID 25178635, 2014). "Tumor cells have some specific over-expressed nuclear antigens relating to their endless proliferation, such as PCNA (proliferating cell nuclear antigen)." (PMID 28809320, 2013). "In contrast, the protein levels of proliferation markers proliferating cell nuclear antigen protein (PCNA) and Ki67 were markedly higher in MMTV-PyVT/HdhQ111/Q111 tumours." (PMID 23300147, 2013). "In immunohistochemical analysis, the CD-MGDG complex group showed a decreased number of proliferating cell nuclear antigen (PCNA)-positive cells and reduction of mitosis in the tumor cells compared with the control group." (PMID 23251235, 2013). "By using immunohistochemical staining for TUNEL and PCNA we found that EESP promoted apoptosis and inhibited proliferation in tumor tissues." (PMID 23800091, 2013). "Proliferating cell nuclear antigen (PCNA) and phosphorylation of protein kinase B (Akt) are markers for tumor growth." (PMID 23956781, 2013). "The positive rate of PCNA in HCC was significantly higher compared to control (P<0.0001) and non-tumor liver tissues (P<0.0001)." (PMID 23292006, 2013).
tumor (continued). "Immunohistochemical analysis of tumor tissue for molecular targets of cell cycle such as CCND1, CCNE1, pRB and PCNA demonstrated a significant decrease in expression level accompanied by a moderate decrease in KI67 in response to P276-00 treatment." (PMID 23414419, 2013). "NKp44 has been shown to interact with the proliferating cell nuclear antigen (PCNA), which is commonly expressed by tumor cells and recruited to cell synapses with NK lymphocytes." (PMID 23518691, 2013). "Immunohistochemical staining for PCNA and Ki-67 further supported the antagonistic effect of PHE and PRO on CRS-induced tumor cell proliferation, indicating that CRS acted in an AR-dependent manner to induce CRC growth in vivo." (PMID 23585898, 2013). "To address tumor biological processes affected by CTSB-shRNA, we investigated proliferation and apoptosis in vivo by PCNA IHC analysis and TUNEL assay." (PMID 24139065, 2013). "To identify tumor proliferation and apoptosis following i.p. injections with LPEI-complexed EGFR specific siRNA, we also examined PCNA expression and apoptosis-induced DNA fragmentation in mice xenografts." (PMID 27234384, 2013). "We observed a striking decrease in the levels of PCNA, cyclin B1 and CDK4 levels and increase in the levels of tumor suppressor E-cadherin and pro-apoptotic protein Bim in the tumor tissue lysates of RLIP76 antisense-treated mice as compared with controls." (PMID 22509328, 2012). "PCNA staining and tissue TUNEL assays showed that both inhibition of cell proliferation and induction of apoptosis contribute to the 125I-induced tumor suppression in nude mouse model." (PMID 22827957, 2012). "Tumor tissues of two combination-therapy groups, especially the group treated with SAHA-DDP/PECE were exhibit much less staining for PCNA compared with that in tumor tissues of mice treated with NS, PECE, SAHA, DDP (p < 0.05)." (PMID 22529899, 2012). "As assessed by PCNA and TUNEL staining, combination treatment showed more significant effects than rapamycin or sorafenib alone in inhibiting tumor cell proliferation and inducing apoptosis of HCC cells (P<0.05 for all)." (PMID 22428038, 2012). "Finally, proliferating cell nuclear antigen (PCNA) which is highly expressed in proliferating cells and associated with malignancy was shown to be recruited in the immunological synapse formed between NK and tumor cells, leading to inhibitory triggering of NKp44 receptors." (PMID 23269924, 2012). "The results showed the protein levels of EGFR and AKT were decreased in the tumor homogenates in both curcumin alone and curcumin combined with gefitinib groups, whereas, the c-MET, cyclin D1, and PCNA were also down-regulated simultaneously." (PMID 21858220, 2011). "Western blotting showed that the expression levels of PCNA and E2F1 were increased by 72.0% (P < 0.017) and 90.0% (P < 0.05), respectively, in the tumor tissues of HFD-fed mice relative to controls." (PMID 21834963, 2011). "The Dnmt1-immunoprecipitation indicated that it was the case because the quantity of PCNA and UHRF1 decreased when the tumor grade increased while the quantity of Dnmt1 immunoprecipitated remained unchanged." (PMID 20613874, 2010). "In mammalian cells, they inhibit lysine 63-type polyubiquitylation of PCNA, inhibit activation of NF-κB by TNF-α and sensitize tumor cells to chemotherapeutic agents." (PMID 20613989, 2010). "To determine the mechanisms of the enhanced efficacy of the combination treatment, we examined its effects on tumor angiogenesis (MVD), tumor cell apoptosis (TUNEL) and proliferation (PCNA)." (PMID 20497582, 2010). "MVD, the number of apoptotic cells and proliferation index in tumor tissues were assessed by CD31, TUNEL and PCNA immunostaining." (PMID 20497582, 2010).
tumor (continued). "In the present study, it was shown that expression of PCNA, MMP-9, VEGF, HGF and IL-6 in tumor tissues in groups I, II and III, which received incomplete RFA, increased remarkably." (PMID 20667141, 2010). "Expression of PCNA, MMP-9, VEGF, HGF and IL-6 in tumor tissues increased significantly in the RFA-treated groups compared with the control group, and of the increases were greatest in the 55°C group (P < 0.05)." (PMID 20667141, 2010). "The average number of PCNA-positive cells for A375P-CXCR1 (1.6-fold; P<0.05) and A375P-CXCR2 (1.8-fold; P<0.05) were significantly higher as compared to A375P-control tumours." (PMID 19401689, 2009). "The positive positions of tumor cells for VEGF, NF-κB, MMP-2 and MMP-9 staining were located in the cytoplasm and for PCNA in the nucleus." (PMID 18983651, 2008). "Tumours were harvested and tissue sections were stained with antibodies against CD31 to determine the microvessel density, PCNA to determine the cycling cells, or TUNEL to determine apoptotic cells." (PMID 14760388, 2004). "The mean PCNA labelling index and mean microvessel count in VEGF-positive tumours were significantly higher than those in VEGF-negative tumours (Wilcoxon rank sum test, P<0.0001; p<0.05)." (PMID 8611409, 1996). "Furthermore, to confirm that upregulated NUB1 reduced PCNA protein expression to suppress HCC cell growth in vivo, we established a subcutaneous tumor model in BALB/c nude mice using Flag-NUB1, Flag-vector HCCLM3, and MHCC97H cells." (PMID 40164590, 2025). "This indicates that IL-6 may promote the expression of PCNA, MMP-9, VEGF, and others following RFA treatment, thereby enhancing proliferation, invasion, and angiogenesis, highlighting its central role in tumor progression." (PMID 41403696, 2025). "PCNA analysis and quantification showed a downward trend in TKI‐treated control‐ETV1 or ‐ERG mice, which is consistent with a potential reduction in proliferation in the treated tumour and therefore with a reduction in tumour volume." (PMID 39374163, 2025). "Both substitutions are localized in the domain responsible for ABH2 binding to proliferating cell nuclear antigen (PCNA), which may be important for regulating ABH2 repair activity in tumor cells." (PMID 41373746, 2025). "NSE, PCNA, and TUNEL staining further confirmed these results: while maraviroc alone had mild effect, its combination with cisplatin suppressed neuroendocrine phenotype, tumor proliferation, and induced apoptosis." (PMID 41152972, 2025). "Finally, we detected the changes in PCNA NEDDylation, PCNA polyubiquitination, and PCNA protein expression in HCCLM3-derived tumor xenografts after TAS4464 treatment." (PMID 40164590, 2025). "Prognostic genes including EZH2, PCNA, and BIRC5 were specifically expressed in epithelial clusters, while CHMP4C, ATP13A2, and ALDOA showed broader expression patterns, supporting their tumor-specific roles." (PMID 40678068, 2025). "Silencing PCNA significantly reduced tumor volume without affecting body weight and led to a notable decrease in Ki67 expression." (PMID 40313621, 2025). "Similarly, high STAT3, JAK, Bcl-2, and PCNA expression in musculoskeletal tumors intensifies JAK/STAT3 signaling activation, accelerating tumor growth, inhibiting apoptosis, and promoting angiogenesis." (PMID 40420174, 2025). "Furthermore, targeting PCNA with the APIM-peptide can modulate key signaling pathways, including the PI3K/Akt and MAPK pathways—two critical pathways that are involved in tumor metastasis due to their extensive crosstalk." (PMID 41024300, 2025). "The results demonstrated that knockdown of ESRRG downregulated PCNA, MMP-2, VIMENTIN, and N-cadherin, while upregulating E-cadherin expression, suggesting that ESRRG may promote tumor migration and invasion by modulating EMT." (PMID 40356747, 2025).
tumor (continued). "We could group the tumor cells phenotypically to proliferating cells (Pan-CK, PCNA; proliferating cell nuclear antigen and Ki67) and apoptotic cells (Pan-CK and PARP; poly ADP ribose polymerase)." (PMID 40728884, 2025). "In double knockout mice lacking EphA4 and EphA7 (EphA4−/− EphA7−/− Smo), MRI and Western blot analyses showed no consistent changes in tumor size, despite correlations between tumor volume, p-Akt, and PCNA levels." (PMID 41200151, 2025). "For instance, it was found that hsa-mir-142 dominates the gene-miRNA-tumor purity correlation, PCNA dominates both the gene-protein-tumor purity correlation and the miRNA-protein-tumor purity correlation, and CCNB1 dominates the miRNA-protein-tumor purity correlation." (PMID 40228208, 2025). "Notably, the A2 tumor area exhibited significant reductions in proteins essential to the DNA replication pathway, including MCM3, MCM4, POLD1, RFC2, and PCNA, all of which are pivotal for maintaining the integrity of DNA replication." (PMID 40076915, 2025). "Additionally, Western Blot analysis revealed changes in the expression of the proliferation marker PCNA, further supporting the regulatory role of SRSF7 in tumor cell proliferation." (PMID 39286028, 2024). "Additionally, IL-6 released from ASCs promotes tumor progression by regulating gene expression involved in proliferation, such as a marker of proliferation Kiel 67 (MKI67) and proliferating cell nuclear antigen (PCNA)." (PMID 39123496, 2024). "Additionally, IHC analysis was performed to assess cell proliferation (Ki-67 and PCNA), apoptosis (p-PI3K, PI3K, p-AKT, AKT), and tumor angiogenesis (CD31)." (PMID 39308674, 2024). "Moreover, literature suggests a correlation between DCE-MRI parameters and key aspects of tumor biology such as angiogenesis, microvessel density (MVD), and proliferating cell nuclear antigen (PCNA) expression." (PMID 39048981, 2024). "Conversely, ANGPTL4 inhibition significantly repressed the tumor weight and volume of SKOV3 cells with low vimentin, PCNA, MMP9, ESM1 and CD34 expression in comparison with the vector and NC groups, which could also be rescued by Colivelin." (PMID 38212795, 2024). "While we did not look at MAPK in our analysis, we observed that there was an increase in proliferative markers EGFR and PCNA by PCR and EGF in serum in patients who received sorafenib/RT, which may enhance the proliferation of tumor cells." (PMID 38542325, 2024). "Additionally, we examined the expression of proliferating cell nuclear antigen (PCNA) in DCBLD1-OV and DCBLD1-KD tumor tissues generated from HeLa cells using IHC." (PMID 38291438, 2024). "Moreover, the levels of proteins involved in cell proliferation (p-Stat3, PCNA, Ki67, and cyclin D1) and cell migration (MMP2) were analyzed in the tumor tissues." (PMID 38441416, 2024). "Moreover, the subcutaneous tumor group of RORα-KO-MFC showed higher Ki-67 and PCNA expression levels than that of CON-MFC group in mice, while these phenomena were also reversed by SR1078." (PMID 38184549, 2024). "Furthermore, tumor cell necrosis and apoptosis were observed by H&E staining and TUNEL immunofluorescence staining, and tumor cell proliferation was assessed using PCNA staining." (PMID 38715912, 2024). "It was indicated that the expression of PCNA was lower in RIPK2-silenced group tumor section, which suggested that knockdown of RIPK2 might inhibit GC cells growth by affecting PCNA." (PMID 38164277, 2024). "Furthermore, findings from an in situ tumor model demonstrated that epirubicin effectively reduced the proliferation of U87-derived tumor tissues in situ, as well as downregulating the expression of KI67, PCNA, and GPX4 in the tissues." (PMID 38561331, 2024). "Importantly, hepatocytes derived from tumour samples consistently showed high expression of malignant genes KRT7 and PCNA." (PMID 37994257, 2024). "Notably, silencing LINC01503 significantly reduced the expression levels of PCNA and CD31+ MVD in tumor tissues." (PMID 39433507, 2024).
tumor (continued). "However, as SCTs are characterized by low proliferation rates, confirmed by PCNA expression only in a few neoplastic SCs, our results showed that NCOA4-driven ferritinophagy is enough to support proliferation in this type of tumor." (PMID 39272404, 2024). "In addition, IHC staining was performed to detect the expression of PCNA, MMP9, and cleaved caspase 3 in tumor tissues." (PMID 38783241, 2024). "Moreover, the subcutaneous tumor group of RORα-KO plus 3PO or RORα-KO plus DHEA revealed a reduction of Ki-67 and PCNA expression levels compared with RORα-KO plus Vehicle group." (PMID 38184549, 2024). "Additionally, PGC-1α knockdown tumors exhibited lower levels of PCNA, P-PKA, and PGC-1α signals relative to the control tumor." (PMID 38782774, 2024). "Furthermore, western blotting revealed that ZN444B significantly decreased the expression of PCNA and increased the expression of cleaved PARP in these primary tumor tissues." (PMID 39010083, 2024). "Furthermore, our analysis of the proliferation-related marker PCNA revealed a dose-dependent decrease in its expression with increasing levels of drug intervention, providing further evidence of ZSTK474’s anti-tumor properties in vivo." (PMID 39466763, 2024). "In addition, the results show that CKS2, PCNA, CHEK1, and NCAPG2 are also involved in the regulation of tumor DNA replication and mismatch repair." (PMID 38937855, 2024). "Tumor sections from the TRF group showed a decrease in mitotic events, reductions in the percentages of PCNA-positive nuclei, and Ki67-positive compared to those from the control group, indicating remarkable mitigation of tumor-associated pathological proliferation." (PMID 37924048, 2023). "Likewise, RNF112 depletion readily increased tumor growth and weight, coupled with elevated expression of FOXM1 and its downstream target genes, as well as that of Ki67 and PCNA in vivo." (PMID 37288663, 2023). "The CCK-8 assay showed that the proliferation of the PLCG2 siRNA group was markedly inhibited, and the level of proliferating cell nuclear antigen (PCNA) was reduced in the PLCG2 siRNA group, which is a tumor cell proliferation factor related to the proliferation ability of cells." (PMID 37031207, 2023). "Proliferating cell nuclear antigen (PCNA) and Ki67 expression were significantly down-regulated in the shAC010883.5 mice compared with the control mice, indicating that AC010883.5 downregulation suppressed tumor growth in vivo, consistent with in vitro." (PMID 37081411, 2023). "A similar pattern of IHC staining for PCNA and FOXA1 protein levels was observed upon SKP2 inhibition, suggesting that SKP2 regulation of FOXA1 may, in turn, drive tumor proliferation and serve as in vivo validation for our in vitro findings." (PMID 37491794, 2023). "Additionally, the overexpression of TRAF6 was found to promote tumor EMT and enhance the expression of PCNA." (PMID 38062041, 2023). "After treatment with Lenvatinib, the positive expression rate of Ki-67 and PCNA in RBE+M2 group was significantly higher than that in RBE group, which may be related to the role of M2 in promoting tumor cell proliferation." (PMID 37809069, 2023). "Tumor growth was reduced as well as β-catenin, transcription factor 4 (TCF4), protein kinase B (AKT), signal transducers and activators of transcription 3 (STAT3), and proliferating-cell nuclear antigen (PCNA) expression." (PMID 36986798, 2023). "Moreover, the gastrodin treatment led to decreased levels of KI67 and PCNA protein expression and increased levels of HOXD10 and ACSL4 in the tumor tissues compared to the DMSO treatment." (PMID 38138552, 2023).